IRGM (immunity related GTPase M)
Diseases named in the same sentence as IRGM in open-access papers (continued):
Sharing a sentence is not in itself a finding about the gene and the disease.
infection (62 papers, 2009 to 2026). The state of being infected such as from the introduction of a foreign agent such as serum, vaccine, antigenic substance or organism. "Instead, IRGM is constitutively expressed at low levels and has been implicated in the regulation of autophagy, including during infections with M. tuberculosis and Salmonella." (PMID 40928289, 2025). "Variation in the human IRGM gene is associated with susceptibility to autoinflammatory diseases but its role in ameliorating inflammatory diseases caused by infections is poorly defined." (PMID 38501887, 2024). "Specifically, previous studies indicate that the loss of murine Irgm1 or human IRGM is consistently associated with defects in autophagy during infection." (PMID 36629440, 2023). "IRGM is a human protein of the immune-associated GTPase family that promotes autophagy during inflammation and infection." (PMID 35280928, 2021). "Functional studies have demarcated a role for IRGM and its mouse orthologue, Irgm1, in regulating autophagy and bacterial outgrowth during pathogenic infection." (PMID 32453761, 2020). "We described recently the autophagy-associated protein IRGM as being a cellular target of MeV for both the induction of autophagy 24 hours post-infection (what correspond to the second autophagy wave), and to improve MeV infectivity." (PMID 24086130, 2013). "However, as the infection progresses to a very late stage in an aging host, the loss of all IRGM proteins becomes detrimental to host survival and is associated with early death." (PMID 36629440, 2023). "We also demonstrate that despite significant changes in the levels of certain disease-associated cytokines in their lungs, mice deficient in all three IRGM proteins show the same level of host protection as wild-type mice until almost 1 year following infection." (PMID 36629440, 2023). "Earlier independent GWASs showed that autophagy gene variants, including autophagy-related gene 16-like 1 (ATG16L1) and immunity-related GTPase M (IRGM) are linked to CD susceptibility highlighting the role of autophagy in controlling infection, inflammation and cancer." (PMID 30669622, 2019). "Unfortunately, genetic replication data on the role of human IRGM polymorphism in infections caused by M. tuberculosis subtypes that have unambiguously been determined by mycobacterial genotyping are not available so far, neither for Caucasian nor for African or Asian study groups." (PMID 19750224, 2009). "Investigation of naturally occurring human genetic variants in ISGs like IRG1, IRGM, or GBP1, to understand how variation in these genes shapes infection outcomes." (PMID 40928289, 2025). "IRGM, being the only molecule that has been shown to regulate autophagy upon infection, thus, becomes greatly important." (PMID 35699756, 2022). "Since we demonstrated that NLRP3, ASC, and IRGM are key regulators for the Golgi shape in homeostasis or infection with HCV, we then examined their regulation upon induction of the components of the inflammasome by a virus-unrelated activator, using nigericin." (PMID 33208442, 2021). "Hepatitis C virus (HCV) infection triggers Golgi fragmentation through the Golgi-resident protein immunity-related GTPase M (IRGM)." (PMID 33208442, 2021). "Primary innate immune response, following the first infection, was initiated by the up-regulation of a single gene, immunity-related GTPase M (IRGM)." (PMID 30873203, 2019). "The second pathway initiates in a few hours after infection and occurs along with the expression of MeV-C protein accompanied by its interaction with autophagy-regulating immunity-Related GTPase family M protein (IRGM)." (PMID 31217023, 2019). "The expression of IRGM was increased on infection of THP-1 cells with Salmonella typhimurium (SL1433)." (PMID 30612879, 2019). "At least, two MeV proteins, MeV-C and MeV-N, have been found to target IRGM (Immunity-Related GTPase M) and interfere with the regulation of infection-mediated autophagy." (PMID 31217023, 2019).
infection (continued). "Western blotting and real-time PCR were performed and we found that CA16 infection triggered significant increases in both the mRNA (P< 0.001) and protein (P< 0.001) levels of IRGM." (PMID 25853521, 2015). "Taken together, these results indicate that IRGM is required for both CA16 infection and 2C or 3C over-expression-induced autophagy." (PMID 25853521, 2015). "Both GKS and IRGM proteins are essential for cell-autonomous resistance to infections with C. trachomatis and T. gondii in mice but fulfill distinct functions in this process." (PMID 23785284, 2013). "IRGM (immunity-related GTPase family M) is a human protein recently highlighted for its contribution to autophagy upon infections." (PMID 23335927, 2012). "Our data clearly indicate a need for IRGM proteins very late during infection." (PMID 36629440, 2023). "However, subsequent studies have identified protective functions for IRGM in autoimmunity or immune responses to infection via its intersection with the autophagy pathway (5, to 9)." (PMID 36629440, 2023). "Instead, it is more likely that the IRGM proteins are involved in controlling the inflammatory environment and tissue damage in the lungs, which appears to be critically important during very late stages of infection and/or advanced host age." (PMID 36629440, 2023). "The human immunity-related GTPase family M (IRGM) protein was shown to be targeted by at least two MeV proteins, C and N. IRGM was described to regulate autophagy mainly in the context of infection, suggesting a pathogen-specific function in autophagy for this protein." (PMID 29186766, 2017). "Interestingly, we found that Immunity-related GTPase family M (IRGM) was crucial for the activation of CA16 infection-induced autophagy; in turn, reducing IRGM expression suppressed autophagy." (PMID 25853521, 2015). "Our results demonstrate that when AMs are treated with Tri-DAP post-infection, the Mtb is enclosed in autophagic vesicles that are positive for autophagy proteins, such as IRGM and LC3, whereas a minimum recruitment of these proteins is observed in the untreated macrophages." (PMID 25253572, 2014). "In addition, the IRGM/murine ortholog IRGM1 may play multiple regulatory functions in addition to autophagy in terms of infection and inflammation." (PMID 30322337, 2019). "To determine whether IRGM is involved in autophagosome formation observed upon MeV, HCV and influenza A infections we have abrogated IRGM expression using specific si-RNA, prior to infection in GFP-LC3-HeLa cells, GFP-LC3-Huh 7.5 or GFP-LC3-A549 cells, respectively." (PMID 22174682, 2011). "Impaired ATG16L1, IRGM or NOD2 expression in macrophages increases intracellular AIEC with enhanced secretion of IL-6 and TNF in response to infection." (PMID 33468624, 2021). "Human IRGM and murine IRGM1 contribute to cell-autonomous defense though autophagy activation via the recruitment of both autophagic and SNARE adaptor proteins during infection." (PMID 30669622, 2019). "However, whether and how IRGM regulates autophagy upon CA16 infection is unknown." (PMID 25853521, 2015). "However, how IRGM regulates autophagy upon infections remains unknown." (PMID 23335927, 2012). "IRGM (Immunity-Related GTPase M) has been shown to interact with components of the autophagy machinery, such as ULK1 and Beclin 1, to promote the formation of autophagosomes in response to infection with intracellular pathogens." (PMID 37443813, 2023). "The late presentation of a survival defect in panIrgm−/− mice, following over 300 days of infection, further suggests that IRGM proteins do not strongly contribute to direct control of Mtb replication, as proposed previously." (PMID 36629440, 2023). "As expected, the down-regulation of ULK-1 and IRGM by siRNA prevented autophagy initiation as shown by the absence of p62 decrease at 6 h post-infection, highlighting an impact of ULK-1 and IRGM on the autophagy process in AIEC-LF82 infected macrophages." (PMID 31694333, 2019).
infection (continued). "A few hours post infection, a second signaling pathway leads to autophagy induction following the expression of MeV-C and its interaction with the autophagy-regulating protein IRGM (Immunity-Related GTPase family M protein)." (PMID 28531150, 2017). "The fact that there appears to be no role for IRGM or for its murine ortholog IRGM1 in the regulation of autophagy in absence of infection suggests a pathogen-specific function in autophagy for these proteins." (PMID 23335927, 2012). "Because murine IRGM proteins exhibit nonredundant functions in host protection during other infections, we tested whether knocking out Irgm3 in an Irgm1−/− background (Irgm1/3−/−) alters host susceptibility to Mtb." (PMID 36629440, 2023). "Furthermore, the role of IRGM could be cell type-specific and, as described for several autophagy-related proteins, IRGM might have non-autophagy-related functions upon infections." (PMID 23335927, 2012). "Of note, unlike the Irgm1 gene in mice, the human Irgm1 ortholog, IRGM, is not responsive to IFN-γ, but interestingly it remains able to induce autophagy upon infection in epithelial cells and macrophages." (PMID 26221063, 2015).
tumor (11 papers, 2011 to 2025). "The expression level of IRGM was positively related to tumor stage and metastasis." (PMID 37705061, 2023). "Collectively, these data imply that under the effect of TAOK3's phosphorylation, KMT2C mediates histone methylation and transcriptionally upregulates the expression of IRGM together with ETV5, and tumor autophagy is augmented consequently." (PMID 37705061, 2023). "After the tumor metastasis assay was performed, we found TAOK3 or ETV5 or IRGM knockdown could robustly reduce the average number of lung metastasis nodules and the size of metastasis nodules indicated by HE staining." (PMID 37705061, 2023).
cancer (9 papers, 2018 to 2026). A tumor composed of atypical neoplastic, often pleomorphic cells that invade other tissues. "Given that generation of alternatively spliced isoforms is frequently associated with drug resistance in cancer therapy, further studies are required to determine the role of IRGM isoforms in diverse tumours." (PMID 35699756, 2022). "Focusing on genes affecting autophagy in cancers, Immunity Related GTPase M (IRGM) attracted our attention." (PMID 37705061, 2023). "Given the plethora of IRGM-related mechanisms that impact autophagy, a pathway that plays a complex role in cancer per se, it is pivotal to establish the precise mechanisms by which IRGM can promote carcinogenesis." (PMID 35699756, 2022). "Immunity-related GTPase M (IRGM) is a novel regulator of PD-L1 that inhibits CD8+ CTL infiltration and function in HCC, resulting in cancer progression." (PMID 40122853, 2025). "Immunity-related GTPase M (IRGM), a critical player in immune regulation, interacts with YBX1 to facilitate PD-L1 transcription, suppressing CD8+ T cell infiltration in HCC and contributing to cancer progression." (PMID 38255791, 2024).
bacterial infections (7 papers, 2014 to 2025). "Studies have also shown that IRGM expression is reduced in patients with CD, and that IRGM-deficient mice exhibit defective xenophagy and are more susceptible to bacterial infections in the gut." (PMID 37443813, 2023). "IRGM proteins regulate inflammation and restrict mycobacterial and other bacterial infections through other autophagy dependent and independent functions." (PMID 40910070, 2025). "To understand the role of IRGM in regulating host response to bacterial infection, we performed RNA‐sequencing (RNA‐seq) experiment with Salmonella typhimurium infected control and stable IRGM shRNA knockdown HT‐29 colon cells." (PMID 36221902, 2022). "On a cellular level, Irgm1 appears to regulate inflammasome activation via selective autophagy, similar to human IRGM, and defects in mitophagy can result in spontaneous interferonopathies and linked susceptibility to bacterial infections." (PMID 38501887, 2024). "Together, it emerges that IRGM has a dual function during bacterial infection." (PMID 36221902, 2022). "None of the SNPs in IRGM, ATG16L1 and TNFRSF1A gene was found to be significantly associated with susceptibility to bacterial infection." (PMID 34407136, 2021).
inflammation (6 papers, 2014 to 2024). Aberrant reaction of the microcirculation characterized by movement of fluid and leukocytes from the blood into extravascular tissues. "Although the exact function of the IRGM genetic polymorphism in CD is not fully understood, a potential explanation is that the IRGM genetic polymorphism may alter the function of IRGM, leading to the invasion of bacteria in vivo, resulting in tissue damage and chronic intestinal inflammation." (PMID 25009628, 2014).
IRGM also shares sentences with these, for which no sentence is quoted: ulcerative colitis (6 papers); Immunodeficiency (4); melanoma (4); parasitic infection (4); non-alcoholic fatty liver disease (3); colorectal cancer (2); experimental autoimmune encephalomyelitis (2); Granuloma (2); infectious disease (2); lymphopenia (2); psoriasis (2); acute liver failure (1); adenocarcinoma (1); age-related macular degeneration (1); ankylosing spondylitis (1); autosomal dominant hereditary pancreatitis (1); chlamydia (1); chronic periodontitis (1); colon carcinoma (1); endometriosis (1); endotoxemia (1); Graves disease (1); Hepatic steatosis (1); Hepatitis (1); influenza (1); intestinal infection (1); lentivirus infection (1); leukopenia (1); lymphoma (1); Mycobacterium avium infection (1).
A further 12 diseases each share a sentence with IRGM in 1 paper.